HMGB1 (high mobility group box 1)
Diseases named in the same sentence as HMGB1 in open-access papers (continued):
Sharing a sentence is not in itself a finding about the gene and the disease.
Sepsis (continued). "During polymicrobial sepsis, lactate could promote high mobility group box-1 (HMGB1) lactylation in a p300/CBP-dependent mechanism and stimulate HMGB1 acetylation through G protein-coupled receptor 81 (GPR81) signaling." (PMID 38993478, 2024). "Nevertheless, the mechanism by which CGK012 is involved in sepsis and systemic inflammation mediated by HMGB1 still remains unknown." (PMID 38474222, 2024). "Additionally, Cel binds to Cys106 in HMGB1, which reduces IL-1β secretion and alleviates the inflammatory response in sepsis." (PMID 39712019, 2024). "According to studies conducted in vivo and in vitro, luteolin can treat sepsis through the destabilization of the heat-shock protein 90 (Hsp90), which destabilizes c-Jun and Akt, thus decreasing the release of HMGB1 and its activation of the inflammatory cascade." (PMID 39126050, 2024). "High mobility group box 1 (HMGB1), as an important pro-inflammatory factor, has been found to be elevated in many metabolic and immune diseases, including sepsis, rheumatoid arthritis, and Alzheimer’s disease, and significantly correlated with their progression and prognosis." (PMID 38481996, 2024). "Similarly, L-lactate-induced lactylation of high-mobility group box-1 (HMGB1) facilitates the release of HMGB1 by macrophage via exosome secretion during polymicrobial sepsis." (PMID 38291438, 2024). "HMGB1 plays a role in the pathogenesis of infectious diseases, such as sepsis and myocarditis." (PMID 38456997, 2024). "Studies have revealed that lactate promotes the lactylation of macrophage HMGB1 in polymicrobial sepsis and that reducing lactate production or inhibiting GPR81-mediated signaling can decrease extracellular HMGB1 levels, enhancing the survival outcomes of polymicrobial sepsis patients." (PMID 39234245, 2024). "Furthermore, Zeng and associates discovered that lncRNA GAS5 forms a regulatory axis with miR-155-5p/SIRT1/HMGB1 in sepsis, with lncRNA GAS5 upregulating SIRT1 to suppress HMGB1 acetylation and release." (PMID 38690282, 2024). "Moreover, a monoclonal antibody specific for TN inhibits the TN/HMGB1 interaction, preventing the cellular uptake of HMGB1 and rescuing animals from lethal sepsis." (PMID 38187250, 2024). "Lactylated HMGB1 is then released by macrophages, disrupting endothelial integrity, increasing vascular permeability, and contributing to endothelial cell barrier dysfunction, thereby promoting sepsis progression." (PMID 39026681, 2024). "Furthermore, the HMGB1 protein expression in the sepsis + remazolam group was lower than the sepsis + saline group." (PMID 38646480, 2024). "Reducing extracellular and circulating HMGB-1 levels could be a potential mechanism for preventing sepsis or progression of the inflammatory response during infection." (PMID 39416736, 2024). "Macrophages in sepsis can induce HMGB1 lactylation by absorbing extracellular lactate through MCTs." (PMID 39026681, 2024). "While the clinical translation of HMGB1-targeted therapies is still in its early stages, preliminary evidence from clinical studies suggests that targeting HMGB1 may have therapeutic potential in sepsis." (PMID 38474222, 2024). "Furthermore, clinical studies have reported that HMGB-1 levels are higher in patients with infection, particularly with pneumonia, peritonitis or severe sepsis." (PMID 39416736, 2024). "HMGB1 shows promise as a biomarker for sepsis diagnosis and prognosis assessment." (PMID 39201697, 2024). "We noted that the HMGB1 expression in the lung tissues increased in sepsis, which could be decreased by BMSC-exos." (PMID 37035447, 2023). "This indicates that enhanced autophagy may promote the secretion of HMGB1 and promote pyroptosis, which may explain the paradoxical effects of autophagy activators in sepsis and deserves further study." (PMID 36658496, 2023). "Studies in macrophages demonstrated that HMGB1 is secreted after lactylation during sepsis." (PMID 37441587, 2023).
Sepsis (continued). "Emodin inhibits SIRT1-mediated HMGB1 protein expression by increasing the mRNA and protein expression of VDR and its downstream molecules, thus alleviating the lung injury caused by sepsis." (PMID 37628912, 2023). "Recent research has indicated that HMGB1 may potentially trigger inflammasome activation through cell interactions in mouse sepsis models." (PMID 38020710, 2023). "HMGB1 has been identified as a key player in the inflammatory response during sepsis." (PMID 37048161, 2023). "They found that the prognosis of sepsis improves after administering monoclonal antibodies targeting HMGB1 without causing immunosuppression." (PMID 37828579, 2023). "HMGB1 acts as an endogenous damage-associated molecular pattern (DAMP) that triggers the innate immune response via binding to toll-like receptor 2 (TLR2), TLR4, and TLR9, which contributes to infection-induced sepsis caused by several pathogens." (PMID 38022511, 2023). "The hypothesis that the composition could be involved in reducing the level of extracellular HMGB1 was first tested in a sepsis model indirectly." (PMID 37764336, 2023). "Various interventions targeting HMGB1 in treating sepsis have been studied recently." (PMID 38026444, 2023). "Although the method of targeting HMGB1 in sepsis has been widely discussed, the detailed mechanism of HMGB1 in inflammation-related signalling pathways remains unclear." (PMID 38026444, 2023). "In the study, mimics miR-22 could remarkably downregulate the LPS-induced increased TLR4, TLR2, MyD88, and p-NF-κB p65 protein expression, which indicated that miR-22 may alleviate sepsis-induced AKI by targeting HMGB1/TLR4/NF-κB signaling pathway." (PMID 35960478, 2023). "The level of HMGB1 is closely related to the prognosis of sepsis." (PMID 36836478, 2023). "All of those indicated that miR-22 could alleviate sepsis-related AKI via targeting the HMGB1/TLR4/NF-κB signaling pathway." (PMID 35960478, 2023). "In our study, PEVs injection significantly increased the serum level of HMGB1 and markers of NETosis in sepsis rats, indicating that PEVs may promote the formation of NETs by regulating HMGB1." (PMID 37559007, 2023). "Notably our finding of caspase-dependent HMGB1 release is consistent with results in e.g. apoptosis-mediated sepsis and for macrophages treated with a proteasome inhibitor." (PMID 37346039, 2023). "HMGB1 is a late-phase inflammatory substrate secreted by activated megakaryocytes in sepsis." (PMID 37223096, 2023). "Interestingly, HMGB1 is also a late mediator of inflammation in sepsis and participates in the amplification of neuroinflammation." (PMID 36906561, 2023). "Correlation analysis between the levels of SII, IL-35 and HMGB-1 and the severity of sepsis." (PMID 36950402, 2023). "A previous report revealed the impact of lactate on HMGB1 in the macrophages in sepsis." (PMID 36709284, 2023). "Therefore, in pathological contexts such as sepsis, HMGB1 constitutes a potential target for clinical interventions." (PMID 37048161, 2023). "Subsequently, Wang and colleagues demonstrated a role for HMGB1 in sepsis, although it has also been reported to participate in the transcriptional regulation of cancer-related genes such as tumor necrosis factor alpha, E-selectin, breast cancer type 1 susceptibility protein, and insulin receptor." (PMID 37009887, 2023). "Furthermore, researchers have discovered that HMGB1 exhibits proinflammatory effects in the treatment of infectious diseases and sepsis." (PMID 37828579, 2023). "Spearman correlation analysis showed that the levels of SII, IL-35, and HMGB-1 were significantly positively correlated with the severity of sepsis (p<0.05), and significantly positively correlated with the prognosis of patients with sepsis (p<0.05)." (PMID 36950402, 2023). "The HMGB1 kinetics suggest that it is a promising target for sepsis as it may offer a broad therapeutic window to treat established septic patients compared to other acute inflammatory cytokines or chemokines." (PMID 36865384, 2023).
Sepsis (continued). "High mobility group protein 1 (HMGB1) levels are predictive of survival in advanced sepsis." (PMID 37904710, 2023). "HMGB1 antibody alters inflammation in murine sepsis model and reduces sepsis mortality." (PMID 35720285, 2022). "green tea rescues mice from lethal sepsis partly by inhibiting HMGB1." (PMID 35720285, 2022). "Day 1 plasma levels of AGE and HMGB1 in patients with sepsis were similar to those in controls." (PMID 35723375, 2022). "One study found that exosomes carrying a large number of damage-associated molecular patterns (DAMPs) were released by secretory cells during sepsis, including high mobility group box 1 (HMGB1), heat shock protein, adenosine triphosphate (ATP) and extracellular RNA, etc.." (PMID 35326456, 2022). "HMGB1 has been shown to contribute to the pathogenesis of sepsis." (PMID 36072408, 2022). "Excellent correlations between mtDNA level and necroptosis mediators (RIPK3, MLKL, and HMGB1) in this study show that a large proportion of plasma mtDNA may be released by necroptosis in sepsis." (PMID 36289650, 2022). "In contrast, HMGB1 could also serve as an advanced mediator of sepsis and have beneficial effects in preclinical sepsis studies." (PMID 35765707, 2022). "The current research proved that in polymicrobial sepsis, lactate could promote macrophage high mobility group box-1(HMGB1) lactylation/acetylation and release exosome, leading to disrupted endothelium integrity and increased vascular permeability." (PMID 36528689, 2022). "During the signal cascade in sepsis, HMGB1 utilizes a variety of membrane receptors." (PMID 36189354, 2022). "miR-181c-5p-HMGB1 signaling pathway could regulate sepsis-induced microglia activation and hippocampal neuron apoptosis." (PMID 35720285, 2022). "xuebijing exhibits protective efficacy on sepsis by inhibiting the expression of HMGB1." (PMID 35720285, 2022). "Anti-HMGB1 treatment, such as anti-HMGB1 polyclonal or monoclonal antibodies, inhibitors (e.g., ethyl pyruvate) and antagonists, can protect against sepsis lethality." (PMID 35720285, 2022). "Hyperinflammation leads to a large amount of DAMPs accumulation, including mtDNA and HMGB1, while DAMPs may play a pivotal role in the formation of immunosuppression in sepsis." (PMID 36106559, 2022). "HMGB1 represents another type of protein displaying pro-inflammatory effect in sepsis disease." (PMID 35463634, 2022). "HMGB1 is a late-stage inflammatory factor that is detectable after ~8 h upon stimulation of monocytes/macrophages by different exogenous factors, suggesting the existence of a wide therapeutic window for treating sepsis (and refs. therein)." (PMID 35454134, 2022). "In conclusion, the effect of GA on the treatment of ALI/ARDS induced by sepsis in rats may be achieved by inhibiting the activation of inflammation-related pathways by inhibiting HMGB1." (PMID 36072408, 2022). "chlorogenic acid attenuates HMGB1 and enhances host defense mechanisms in murine sepsis." (PMID 35720285, 2022). "Therefore, pharmacological and genetic inhibition of inflammasome signaling pathways can attenuate the release of HMGB1 and protect mice from sepsis or ischemia/reperfusion damage." (PMID 35217834, 2022). "This also suggests that infiltration of macrophages could inhibit lung tissue-specific CD4+CD25+Foxp3+ Tregs via HMGB1/PTEN/β-catenin axis in sepsis-induced ALI." (PMID 35281010, 2022). "As an important late inflammatory factor, HMGB1 is involved in the pathogenesis of sepsis." (PMID 35720285, 2022). "HMGB1 expression negatively correlated with miR−205−5b expression in LPS-induced sepsis." (PMID 35720285, 2022). "miR-205 agonist could improve the pathological morphology in the sepsis rats with renal injury, improve renal cell apoptosis, and inhibit the protein levels of HMGB1 and PTEN in renal tissues." (PMID 35720285, 2022). "The first report linking the HMGB1 protein to infection and disease progression was in sepsis." (PMID 36016387, 2022).
Sepsis (continued). "We examined if CN could suppress HMGB1-induced excessive permeability and if the reduction of HMGB1 in response to LPS treatment increased the survival rate in a mouse model of sepsis." (PMID 35216180, 2022). "Furthermore, the mtDNA copy number showed excellent correlations with those of necroptosis mediators, including RIPK3, MLKL, and HMGB1, which implies a link between plasma mtDNA and necroptosis in sepsis." (PMID 36289650, 2022). "Overall, we conclude that the suppressed release of HMGB1 and the increased survival rate of mice with CLP-induced sepsis caused by CN may be an effective pharmaceutical treatment for sepsis." (PMID 35216180, 2022). "In cellular inflammation models, decreasing HMGB1 alleviates LPS-induced sepsis and MODS in vitro." (PMID 35720285, 2022). "Further, Hmgb1, the so-called alarmins proteins in stressed or activated inflammatory cells, can also be co-modified by L-Lactyl-CoA and acetyl-CoA in polymicrobial sepsis." (PMID 36092712, 2022). "Next, we focused on the role of exosomal HMGB1 during sepsis." (PMID 34363018, 2022). "Previous research uncovered that XBJ can down-regulate HMGB1 expression induced by sepsis." (PMID 36467039, 2022). "Activated PTEN inhibits PI3K/PDK1/Akt signaling, which further suppresses β-catenin activity to modulate regulatory T cells, suggesting that HMGB1/PTEN/β-catenin signaling in the induction of regulatory T cells represents a novel therapeutic strategy in the treatment of sepsis-induced lung injury." (PMID 35814272, 2022). "chloroquine inhibits HMGB1 inflammatory signaling and protects mice from lethal sepsis." (PMID 35720285, 2022). "In addition, increased serum HMGB1 levels positively correlate with mortality in the late phase of sepsis." (PMID 34363018, 2022). "In addition, recent studies have shown that isoproterenol can inhibit the release of HMGB1 and improve the survival rate of mice with sepsis by mediating HO-1 induction through Nrf2 translocation." (PMID 35899121, 2022). "In addition, while it is reported that aerobic glycolysis can stimulate HMGB1 acetylation in macrophages, little is known about the roles of lactate in HMGB1 acetylation and release during sepsis." (PMID 34363018, 2022). "HMGB1 activates the innate immune system and promotes inflammation in conditions such as sepsis." (PMID 35720285, 2022). "In animal models of fatal endotoxemia or severe sepsis, heparin inhibited the LPS cytoplasmic transmission by blocking the hMGB1-LPS interactions and decreasing the heparinase-induced glycocalygeal degradation in macrophages, thereby attenuating the overactivation of this harmful cascade." (PMID 36189354, 2022). "Given that HMGB1 is a late phase factor in lethal sepsis, substances that inhibit the secretion of HMGB1 from damaged cells and stimulated immunocytes may be promising candidates for the treatment of lethal septic diseases." (PMID 35216180, 2022). "Nevertheless, how CN interacts with sepsis and systemic inflammation mediated by HMGB1 is still unknown." (PMID 35216180, 2022). "In vitro, paclitaxel could prevent LPS-induced AKI by regulating lncRNA MALAT1/miR-370-3p/HMGB1 axis, suggesting that paclitaxel may be used as a therapeutic drug to reduce sepsis-related AKI." (PMID 35720285, 2022). "miR-181-5p might function as an HMGB1 antagonist for alleviating sepsis-induced systemic inflammation." (PMID 35720285, 2022). "Movement of HMGB1 between these compartments is a dynamic process, and it can be actively or passively released into the extracellular space during trauma, hemorrhagic shock, stress, and/or sepsis." (PMID 35053249, 2022). "Indeed, in a cecal ligation and puncture (CLP)-induced sepsis model, we observed significantly increased serum lactate and HMGB1 levels by 170 and 183% in CLP septic mice when compared with sham controls." (PMID 34363018, 2022).
Sepsis (continued). "Thus, they suggested HMGB1 as a marker of systemic inflammation in KD and as having a possible role in mediating immune response in KD as in sepsis." (PMID 35558368, 2022). "Accordingly, inhibition of HMGB1 translocation and/or secretion therapeutically may have a protective effect on acute lung injury induced by sepsis." (PMID 36081910, 2022). "To determine whether increased lactate levels could regulate the serum HMGB1 production during sepsis, we increased serum lactate levels by i.p. injection of lactate to mice 6 h after induction of sepsis and examined serum HMGB1 and lactate levels." (PMID 34363018, 2022). "HMGB1 can be involved in inflammation, migration, invasion, proliferation, differentiation, and tissue regeneration but it can also be responsible for the deleterious effects observed in contexts like diabetes, ischemia-reperfusion injury, or sepsis." (PMID 35053332, 2022). "The present study investigated whether lactate could promote HMGB1 lactylation and acetylation in macrophages during polymicrobial sepsis." (PMID 34363018, 2022). "HMGB1, an influential factor in sepsis, is secreted from injured cells and stimulated immunocytes." (PMID 35216180, 2022). "HMGB1 is released not only in trauma, but also in sepsis and endotoxemia." (PMID 36726379, 2022). "Our data suggest that glycolysis-derived lactate and lactate-associated signaling could be potential targets for suppressing HMGB1 release from macrophages and improving survival outcome in polymicrobial sepsis." (PMID 34363018, 2022). "glycyrrhizin may protect rats against sepsis by blocking the interaction of HMGB1 with cell surface receptors and HMGB1-mediated inflammatory responses." (PMID 35720285, 2022). "A growing body of evidence has proved that HMGB1 could be elevated in the settings of sepsis, shock, and other inflammatory diseases, if the strategies to reduce HMGB1 activity have a therapeutical effect that has not yet been validated." (PMID 36138855, 2022). "inhibiting expression of miR-25 may serve a role in up-regulating HMGB1 expression and resulting in sepsis." (PMID 35720285, 2022). "HMGB1 plays a critical role in multiple organ dysfunctions when released extracellularly in sepsis." (PMID 34363018, 2022). "miR-181b directly targets HMGB1, and down-regulating HMGB1 in sepsis could reduce inflammatory factors and myocardial injury and inhibit cardiomyocyte apoptosis." (PMID 35720285, 2022). "rhododendron brachycarpum may produce a unique scaffold that is developed into a drug mitigating HMGB1-induced vascular pro-inflammation and alleviating severe sepsis and related manifestations." (PMID 35720285, 2022). "xuebijing ameliorates sepsis-induced ALI by down-regulating HMGB1 and RAGE expressions in mice." (PMID 35720285, 2022). "GP could inhibit myocardial HMGB1 translocation in severe sepsis and result in attenuation of cardiac dysfunction and improve outcome." (PMID 35720285, 2022). "miR-129-5p protects against sepsis-induced ALI by decreasing HMGB1 expression." (PMID 35720285, 2022). "ketamine protects rats against HMGB1-RAGE activation in a rat model of sepsis-induced ALI, which may partially result from reductions in NF-κB and MAPK." (PMID 35720285, 2022). "The activation of these pathways has been frequently observed in different pathologies in which HMGB1 plays an important role, such as cancer, sepsis, neurological and cardiac diseases, suggesting how this axis could represent an important therapeutic target." (PMID 35053332, 2022). "HMGB1 rearranges the actin cytoskeleton into a contractile phenotype through the downstream effector of late action, disrupting the endothelial cell barrier and increased mortality in sepsis." (PMID 36081910, 2022). "miR-205−5b inhibites HMGB1 expression in LPS-induced sepsis." (PMID 35720285, 2022).